PTBP1 (polypyrimidine tract binding protein 1)
Diseases named in the same sentence as PTBP1 in open-access papers (continued):
Sharing a sentence is not in itself a finding about the gene and the disease.
non-small cell lung carcinoma (9 papers, 2019 to 2024). A group of at least three distinct histological types of lung cancer, including non-small cell squamous cell carcinoma, adenocarcinoma, and large cell carcinoma. "Moreover, circEPB41L2 blocks the progression and metastasis in non-small cell lung cancer by promoting TRIP12-triggered PTBP1 ubiquitylation." (PMID 38715012, 2024). "Similarly, circGLIS3 promoted non-small cell lung cancer phenotypes by affecting miR-644a/PTBP1 signaling." (PMID 34716285, 2021). "Exosomal circ-RACGAP1 recruiteS PTBP1 to induce RIF1 deacetylation, which then activates the Wnt/β-catenin pathway and prmotes the proliferation of non-small cell lung cancer (NSCLC) cells." (PMID 37525158, 2023).
gallbladder cancer (7 papers, 2019 to 2024). "In gallbladder cancer, circFOXP1 binds with PTBP1 and enhances the capacity of PTBP1 to bind to PKLR mRNA." (PMID 39550559, 2024). "CircFOXP1 contributed to gallbladder cancer progression by interacting with PTBP1 and sponging miR-370." (PMID 34986849, 2022). "Compared with normal tissues, PTBP1 was upregulated in gallbladder cancer tissues and the protein and mRNA of PKLR was also upregulated in gallbladder cancer tissues." (PMID 31623628, 2019). "CircFOXP1 can interact with PTBP1, inhibit the 3′ UTR and CDS regions of PTBP1-binding PKLR mRNA, promote the expression of PKLR, and accelerate the appearance and development of gallbladder cancer." (PMID 39199340, 2024). "In gallbladder cancer, circFOXP1 stimulated the cell Warburg effect by interacting with the RBP polypyrimidine Tract-binding protein 1 (PTBP1), which significantly increased the expression of pyruvate kinase PKLR and protected PKLR mRNA from degradation." (PMID 33710802, 2021). "CircFOXP1 interacts with PTBP1, which binds to the 3′-UTR region and coding region of PKLR mRNA (UCUU sequences) to impair the decay of PKLR mRNA, thereby promoting Warburg effect in gallbladder cancer progression." (PMID 34168116, 2021).
brain tumors (6 papers, 2021 to 2025). "PTBP1 can also affect the permeability of the blood–brain tumour barrier through the PTBP1/circRNA_001160/miR‐195‐5p/ETV1 axis of action." (PMID 40579921, 2025). "One study demonstrated that the interaction of lnc00462717 with PTBP1 inhibited the miR‐186‐5p/occludin pathway and reduced the permeability of the blood–brain tumour barrier." (PMID 40579921, 2025). "The expression levels of PTBP1 have been found to be elevated in brain tumors, and different malignant cell lines." (PMID 35600383, 2022). "Importantly, analysis of primary brain tumor samples from our patient cohort and from publicly available databases demonstrated that PTBP1 is abundantly expressed in brain tumors, particularly in GBM." (PMID 34548489, 2021). "Moreover, PTBP1 is a potent driver of brain tumor growth and invasiveness." (PMID 38918441, 2024).
lung adenocarcinoma (6 papers, 2019 to 2025). A carcinoma that arises from the lung and is characterized by the presence of malignant glandular epithelial cells. "Here, it is shown that PTBP1 is associated with the facilitation of tumor growth and the prognosis in lung adenocarcinoma (LUAD)." (PMID 39057099, 2024). "Survival analysis indicated that overexpression of PTBP1 generally predicted poor overall survival in patients with tumors such as adrenocortical carcinoma, liver hepatocellular carcinoma, lung adenocarcinoma, and skin cutaneous melanoma." (PMID 36595978, 2022). "However, the significance of the miRNA-195-5p/polypyrimidine tract-binding protein 1 (miRNA-195-5p/PTBP1) axis in the progression of lung adenocarcinoma (LUAD) remains unclear." (PMID 35600383, 2022).
ovarian tumor (6 papers, 2014 to 2022). "Furthermore, high expression of PTBP1 has been demonstrated to be associated with aggressive behavior of several types of cancer, especially in glioma and ovarian tumors." (PMID 28404950, 2017). "Expression levels of PTBP1 have been found elevated in brain tumors, ovarian tumors, breast cancers and different malignant cell lines." (PMID 28404950, 2017). "Another study demonstrated that knockdown of PTBP1 expression by siRNA impairs the growth of ovarian tumor cells and diminishes their malignant potential, indicating that overexpression of PTBP1 can be an important component of a multistep process of carcinogenesis." (PMID 24945256, 2014).
Alzheimer disease (5 papers, 2014 to 2024). A progressive, neurodegenerative disease characterized by loss of function and death of nerve cells in several areas of the brain leading to loss of cognitive function such as memory and language. "Previous studies have indicated that PTBP1 plays an important role in cancer progression, Alzheimer’s disease and cardiac fibrosis." (PMID 37055817, 2023).
prostate carcinoma (5 papers, 2011 to 2024). A carcinoma that arises from epithelial cells of the prostate gland. "PTBP1 is overexpressed in prostate cancer and is associated with poor prognosis." (PMID 39287090, 2024). "PTBP1 markedly reinforced genomic DNA stability to desensitize prostate cancer cells to irradiation." (PMID 39287090, 2024). "In prostate cancer, PTBP1 was known to affect the clinical response to Androgen-deprivation therapy, indicting PTBP1 plays vitally regulatory roles in clinical cancer diagnosis and treatment." (PMID 36447254, 2022). "RASSF2, which is a tumor-suppressor in the prostate cancer mouse model, might be coregulated by FXR1, FXR2, HNRNPA1, PTBP1, G3BP1, HNRNPF, and SRSF7." (PMID 32316190, 2020). "Mechanistically, PTBP1 binds to RALY and together regulates alternative splicing of DNMT3B to increase DNMT3B‐L accumulation, leading to hypermethylation of the DUSP2 promoter and downregulation of its expression, and then increasing radioresistance of prostate cancer." (PMID 39287090, 2024).
pulmonary fibrosis (5 papers, 2022 to 2025). Chronic progressive interstitial lung disorder characterized by the replacement of the lung tissue by connective tissue, leading to progressive dyspnea, respiratory failure, or right heart failure. "Altogether, these data reveal that modulation of radiation-induced EMT and lung fibrosis by treatment with LGG associates with a decrease in SNHG17 expression and the inhibition of SNHG17/PTBP1/Nothch1 axis." (PMID 36635762, 2023). "Importantly, HOTTIP was noticeably upregulated in patients with pulmonary fibrosis and enhanced lung tissue fibrosis via miR-744-5p/PTBP1." (PMID 38238652, 2024). "Moreover, SNHG17 is an lncRNA that promotes radiation-induced EMT and lung fibrosis through stabilizing PTBP1 expression and activating Notch1 expression." (PMID 36635762, 2023). "Mechanistically, SNHG17 can stabilize PTBP1 expression through binding to its 3′UTR, whereas the activated PTBP1 can bind with the NICD part of Notch1 to upregulate Notch1 expression and aggravated EMT and lung fibrosis post radiation." (PMID 36635762, 2023).
Sepsis (5 papers, 2023 to 2025). Sepsis is defined as life-threatening organ dysfunction caused by a dysregulated host response to infection. "CircEXOC5 stabilizes ACSL4 mRNA by interacting with polypyrimidine tract-binding protein 1 (PTBP1),facilitating ferroptosis in the context of sepsis-induced acute lung injury." (PMID 40078365, 2025). "For instance, previous study in our lab has illustrated that circEXOC5 exacerbates ferroptosis by modulating PTBP1/ACSL4 axis in sepsis-induced ALI." (PMID 38395749, 2024). "The signaling cascade circEXOC5/PTBP1/Skp2/Runx2, by essentially regulating inflammation and autophagy in MPVECs, aggravates sepsis-induced ALI." (PMID 36302650, 2023). "CircEXOC5 binds to PTBP1 to promote ACSL4 mRNA stability, leading to ferroptosis in sepsis-induced acute lung injury." (PMID 37686142, 2023).
cholestasis (4 papers, 2019 to 2025). Impairment of the bile flow caused by obstruction within the liver, or outside the liver in the bile duct system. "Maternally expressed 3 (MEG3) serves as a guide RNA scaffold by recruit polypyrimidine tract binding protein 1 (PTBP1) to destabilize Shp mRNA to cause cholestasis." (PMID 32670859, 2020). "Corresponding to the induction of H19 in cholestasis, we examined PTBP1 mRNA expression in BA-insulted cells in vitro and found that it was significantly decreased by the treatments with several BAs in MSC cells." (PMID 30778047, 2019). "Taken together, this study revealed for the first time that H19 promoted let-7 expression by decreasing PTBP1’s expression level and its binding to the let-7 precursors in cholestasis." (PMID 30778047, 2019). "Furthermore, H19-mediated cholestasis involves polypyrimidine tract-binding protein 1 (PTBP1) downregulation and subsequent aberrant let-7 expression, suggesting a multi-layered regulatory network." (PMID 40832105, 2025). "Next, we examined whether H19 affected PTBP1 expression in BDL-induced cholestasis." (PMID 30778047, 2019). "We find that H19 significantly induces let-7a-5p/7d-5p/7f-5p in cholestatic mouse livers and facilitates the interactions between PTBP1 and pre-let-7d/pre-let-7–7a-1 in vitro, suggesting that the PTBP1/let-7 miRNAs may be involved in the progression of cholestasis." (PMID 30778047, 2019).
clear-cell renal cell carcinoma (4 papers, 2017 to 2022). "Literature search has revealed different targets of miR-124 in different tissues and tumor types, such as Foxq1 in nasopharyngeal cancer, CCAAT/enhancer-binding protein-α in macrophages, PTBP1 in neuronal differentiation, and CAV1 and FLOT1 in renal clear cell carcinoma." (PMID 28212569, 2017).
colorectal tumors (4 papers, 2016 to 2022). "Our results suggested that PTBP1 and PTBP1-associated miR-1 and -133b are crucial molecules for the maintenance of the Warburg effect in colorectal tumors." (PMID 26980745, 2016). "Overexpression of PTBP1 in colorectal tumors was attributed to the downregulation of muscle-specific miR-1 and miR-133b, which target the PTBP1 3′UTR." (PMID 34769047, 2021). "Another important conclusion of this study is that PTBP1 is a very crucial oncogene in the development of colorectal tumors." (PMID 26980745, 2016). "In this study, we indicated that PTBP1 was very frequently over-expressed in colorectal tumors and even in adenomas." (PMID 26980745, 2016). "Furthermore, PTBP1 was highly expressed in most of the 30 clinical colorectal tumor samples examined, even in adenomas." (PMID 26980745, 2016). "Finally, to investigate whether PTBP1 functioned as an oncogene clinically, we examined the expression level of PTBP1 in clinical colorectal tumor samples." (PMID 26980745, 2016). "Next, we examined protein expression levels of PTBP1, hnRNPA1, and SRSF3 in clinical colorectal tumor samples." (PMID 30279379, 2018).
injury (4 papers, 2021 to 2025). Damage inflicted on the body as the direct or indirect result of an external force, with or without disruption of structural continuity. "Our findings help to elucidate the role of Ptbp1 knockdown in nerve injury and regeneration and highlight the potential therapeutic value of targeting Ptbp1 in the treatment of nerve injury." (PMID 40702752, 2025). "The lncRNA MEG3 can recruit PTBP1 to regulate small heterodimer partner mRNA stability and cholestatic liver injury." (PMID 34706749, 2021). "CircEXOC5 can directly bind to RNA-binding protein polypyrimidine tract binding protein 1 (PTBP1) to enhance ACSL4 mRNA stability, leading to ferroptosis in sepsis-induced acute lung injury." (PMID 37686142, 2023).
renal cell carcinoma (4 papers, 2022 to 2025). "Our previous study revealed that PTBP1 promoted the progression of renal cell carcinoma by stimulating the hypoxia inducible factor-1α pathway." (PMID 38341427, 2024). "Our previous work exhibited that PTBP1 knockdown can suppress the development and metastasis of renal cell carcinoma." (PMID 38341427, 2024).
Stroke (4 papers, 2021 to 2026). Sudden impairment of blood flow to a part of the brain due to occlusion or rupture of an artery to the brain. "Functional studies demonstrated that PTBP1-mediated suppression of circSCMH1 exacerbates post-stroke brain injury." (PMID 41328340, 2026). "Subsequent immunoblotting analysis revealed elevated PTBP1 levels in the AIS patient samples compared to those of non-stroke controls." (PMID 41328340, 2026). "Taken together, these findings demonstrate elevated PTBP1 levels and diminished circSCMH1 expression post-stroke, suggesting a potential regulatory mechanism involving circSCMH1 biogenesis in stroke pathology." (PMID 41328340, 2026). "This insight highlights the significance of PTBP1 in the pathological mechanisms following ischemic stroke, offering new perspectives on novel therapeutic targets for stroke." (PMID 41328340, 2026). "This work not only advances our understanding of circular RNA biogenesis in pathological conditions but also positions PTBP1 as a potential therapeutic target for improving stroke recovery." (PMID 41328340, 2026). "Collectively, these results showed that targeting PTBP1 in astrocytes significantly enhances functional recovery after stroke by mitigating astrocyte activation and structural deficits." (PMID 41328340, 2026). "In the present study, therefore, we examined the therapeutic potential of suppressing Ptbp1 messenger RNA (mRNA) by viral transduction in a post-stroke dementia mouse model." (PMID 39227632, 2024). "The results collectively indicate that astrocytes are the primary cell type exhibiting significant upregulation of Ptbp1 mRNA and PTBP1 protein after ischemic stroke, suggesting a potentially crucial role for astrocytic PTBP1 in regulating circSCMH1 expression in response to stroke-induced injury." (PMID 41328340, 2026). "It is plausible that these proteins, either independently or through interactions with PTBP1, could influence stroke prognosis." (PMID 41328340, 2026). "Collectively, these findings suggest that the abnormal upregulation of PTBP1 in astrocytes may play a critical role in the pathogenesis and progression of stroke." (PMID 41328340, 2026). "Observing upregulated circSCMH1 in astrocytes post-stroke, we thus investigated whether PTBP1 modulation alters astrocyte reactivity." (PMID 41328340, 2026). "Next, we investigated the impact of PTBP1 on the functional recovery of stroke mice." (PMID 41328340, 2026). "Immunofluorescence staining further confirmed that the PTBP1 is significantly increased in astrocytes following ischemic stroke, evidenced by the enhanced colocalization of PTBP1 with the astrocyte marker GFAP in the peri-infarct region in PT and tMCAO stroke model." (PMID 41328340, 2026). "The therapeutic potential of suppressing polypyrimidine tract-binding protein 1 (Ptbp1) messenger RNA by viral transduction in a post-stroke dementia mouse model has not yet been examined." (PMID 39227632, 2024). "Previous studies have identified several targets of miR-124, such as PTB/hnRNP I (PTBP1) and SRY-box transcription factor (Sox9), which participate in neuronal differentiation; and Jagged1 (JAG1), which mediates neurogenesis in stroke." (PMID 33841091, 2021). "Importantly, our results demonstrated a significant elevation in Ptbp1 expression specifically within astrocytes following a stroke, while no significant changes in expression were observed in other cell types before or after the stroke." (PMID 41328340, 2026). "In the present study, we demonstrated that AAV-pGFAP-CasRx-Ptbp1 crossed the BBB and generated new mCherry/NeuN double-positive neuron-like cells, its origin could be mCherry/GFAP double-positive astrocyte-like glia, in the hippocampus of post-stroke dementia mouse model." (PMID 39227632, 2024).
aneurysm (3 papers, 2021 to 2025). Bulging or ballooning in an area of an artery secondary to arterial wall weakening. "Hypomethylation of several genes, including CXCR4, OSM, GSTA4, MAP3K10, ADAMTS, PTBP1, and PNPLA6,61, –63,65,67,71 has been identified as being associated with the aneurysm formation." (PMID 41342741, 2025). "CircHipk3 serves a dual role in augmenting macrophage pyroptosis by interaction with Stat3, increase the NLRP3 level, and by binding Snd1 to promote Ptbp1 mRNA degradation to inhibit autophagy, thereby inducing aneurysm formation and progression." (PMID 39601144, 2024). "However, the following subgroup analysis stratified by ruptured and unruptured aneurysms in patients revealed no statistical difference in PTBP1 methylation between ruptured IA and unruptured IA groups (p > 0.05)." (PMID 34295240, 2021).
bladder urothelial carcinoma (3 papers, 2020 to 2023). "Studies had proved that overexpression of MAFG-AS1 can upregulate the expression of polypyrimidine tract-binding protein 1 (PTBP1) through promoting its stability mediated by bound HuR, thus promoting the progression of bladder urothelial carcinoma (BUC) via regulation of the HUR/PTBP1 axis." (PMID 35513366, 2022).
insulinoma (3 papers, 2010 to 2021). "PTBP1 (polypyrimidine tract-binding protein 1) is an RNA-binding protein that, in insulinoma INS-1 cells, enhances the stability and translation of mRNAs encoding insulin granule proteins." (PMID 21063464, 2010). "Moreover, the overexpression of BAT-derived miR-92 in INS-1 cells (a rat insulinoma cell line) reduces insulin by the downregulation of polypyrimidine tract binding protein 1 (PTBP1)." (PMID 33923175, 2021). "Glucose stimulation of rat insulinoma INS-1 cells for 2 h led to a significant increase in the amounts of insulin 1 and 2 and the secretory granule markers ICA512/IA-2, PC1/3 and PC2 mRNAs co-immunoprecipitated with Polypyrimidine Tract Binding Protein 1 (PTBP1)." (PMID 31430885, 2019).
intrahepatic cholangiocarcinoma (3 papers, 2023 to 2025). A carcinoma that arises from the intrahepatic bile duct epithelium in any site of the intrahepatic biliary tree. "Circular RNA (circRNA) circMBOAT2, located on chromosome 2p25, promotes lipid metabolic reprogramming in intrahepatic cholangiocarcinoma (ICC) through the circMBOAT2/PTBP1/FASN axis." (PMID 40392981, 2025).